FBXW7 (F-box and WD repeat domain containing 7)
Diseases named in the same sentence as FBXW7 in open-access papers (continued):
Sharing a sentence is not in itself a finding about the gene and the disease.
esophageal cancer (11 papers, 2016 to 2024). A primary or metastatic malignant neoplasm involving the esophagus. "Decreased expression of FBXW7 attenuates miR-223 mediated promotion of esophagus cancer cell migration and invasion and was associated with worse outcome." (PMID 31064356, 2019). "Low FBXW7 expressions in tumor as compared to normal tissues were significantly correlated with poor prognosis of overall survival in CRCs and esophageal cancer (EC) patients." (PMID 28769798, 2017). "Furthermore, the loss of E3 ubiquitin ligase FBXW7 function has also been shown to lead to an increase in ANXA2 expression levels, thus promoting the malignant progression of esophageal cancer through ERK activation." (PMID 38658569, 2024). "Firstly, we detected the expression of FBXW7 in six esophageal cancer cell lines by Western blot and found that FBXW7 presented strong expression in less malignant cell lines such as KYSE70 and KYSE180, but lower in the higher malignant KYSE30, KYSE150 and KYSE510." (PMID 36991467, 2023). "In esophageal cancer, current studies focus on the regulation of FBXW7 expression." (PMID 36991467, 2023). "Notably, a previous study showed that miR-27a promoted the growth of esophageal cancer by targeting FBXW7." (PMID 32159214, 2020). "Moreover, silencing of FBXW7 inhibited polyubiquitination of ZFP36, increased ZFP36 protein expression, and reduced VEGF-C expression in OTUD3-silencing esophageal cancer cells, suggesting that downregulation of FBXW7 rescues the effects of OTUD3 depletion in ZFP36 and VEGF-C expression." (PMID 34853315, 2021). "Indeed, FBXW7 promoted the ubiquitination and degradation of ZFP36 in esophageal cancer cells." (PMID 34853315, 2021). "Interestingly, the FBXW7 E3 ligase was not affected by CSE or nicotine in esophageal cancer cells." (PMID 34853315, 2021).
renal carcinoma (11 papers, 2017 to 2025). A carcinoma arising from the epithelium of the renal parenchyma or the renal pelvis. "FBXW7 plays a critical role in inducing the degradation of nuclear factor of activated T cells 1 (NFAT1) in renal cancer cells, a process regulated by glycogen synthase kinase-3β (GSK-3β)." (PMID 40534867, 2025). "The downregulation of FBXW7 induced by FOXA1 reduction is responsible for the sunitinib-resistant in renal cancer." (PMID 36998461, 2023). "In RCC, upregulation of FBXW7 can lower the level of c-Myc and c-Jun, thereby reducing the proliferation rate of renal cancer cells and further prompted apoptosis." (PMID 30791487, 2019). "Notably, increased FBXW7 mutations were observed in patients of African descent, while VHL and PBRM1 mutations were decreased in African-origin renal cancer patients." (PMID 40564200, 2025). "This regulatory mechanism underscores the importance of FBXW7 in controlling NFAT1 levels and its potential role in renal cancer progression." (PMID 40534867, 2025). "In mice injected with renal carcinoma cells, the expression of FBXW7 exhibits circadian oscillations in the tumours, driven by DBP, which binds to and transactivates Fbxw7 in a rhythmic fashion." (PMID 36142478, 2022). "Previous evidence has shown that FBXW7 functions as a tumor suppressor in different human cancers, including non-small cell lung cancer (NSCLC) and renal cancer." (PMID 35094292, 2022). "In CC cells and renal cancer cells, miR-182-5p directly binds to the 3’-UTR of FBXW7 mRNA and inhibits the expression of wild-type FBXW7 proteins because FBXW7 contains a hypothesized binding site for miR-182-5p in its 3’-UTR." (PMID 36998461, 2023).
renal cell carcinoma (11 papers, 2015 to 2025). "Our previous study confirmed that circPSD3 blocked EMT activation, and related reports also documented that FBXW7 regulates EMT in renal cell carcinoma." (PMID 35295711, 2022). "We aim to investigate the potential influence of FBXW7 overexpression on renal cell carcinoma (RCC) metastasis." (PMID 29097832, 2017). "miR-92a-3p induced the proliferation of renal cell carcinoma by targeting FBXW7." (PMID 34869346, 2021). "As FBXW7 is frequently downregulated in cancer cell lines, functional studies revealed that a higher level of FBXW7 dramatically inhibited migration and invasiveness of renal cell carcinoma." (PMID 33800394, 2021). "Research reveals that FBXW7 is involved in renal cell carcinoma (RCC) cell invasion and metastasis by virtue of suppressing EMT, which has great potential for future therapeutic targets." (PMID 35515121, 2022). "It was recently reported that FBXW7 is frequently downregulated in cancer cell lines and tumor tissues, such as renal cell carcinoma (RCC), compared with normal tissues and normal cell lines." (PMID 30999935, 2019). "In contrast, ectopic expression of FBXW7 in renal cell carcinoma (RCC) cells reduces c-Jun expression and leads to reduced cellular proliferation and apoptosis." (PMID 30086763, 2018). "Whereas, the functional roles of FBXW7 in metastasis and EMT processes of renal cell carcinoma (RCC) are rarely reported, and the molecular pathways by which FBXW7 regulates RCC metastasis and EMT merit investigation." (PMID 29097832, 2017). "Furthermore, no study has examined the role of FBXW7 in renal cell carcinoma (RCC) metastasis and EMT." (PMID 29097832, 2017).
chronic myeloid leukemia (10 papers, 2014 to 2022). "Fbxw7 controls leukemia-initiating cells in chronic myelogenous leukemia and chronic myeloid leukemia (CML) by regulating c-Myc ubiquitination." (PMID 29555946, 2018). "FBXW7, for example, plays an integral role in hematopoietic stem and progenitor cell (HSPC) self-renewal, and its loss has been linked to drug-resistant T-cell acute lymphoblastic leukemia, whereas loss of chronic myeloid leukemia (CML) inhibits the initiation and progression of disease." (PMID 31684170, 2019). "Thus, in experimental models of chronic myeloid leukemia (CML), genetic ablation of FBXW7 in quiescent leukemic stem cells reprograms them to re-enter the cell cycle and the cells become susceptible to imatinib." (PMID 31921125, 2019).
squamous cell carcinoma (10 papers, 2014 to 2022). A carcinoma arising from squamous epithelial cells. "As PIK3CA and FBXW7 genes are significantly mutated in other HPV associated squamous cell carcinomas, they could act as driver events in this histological type of cancers." (PMID 29416628, 2018). "They found novel somatic mutations in the MAPK1 gene (8%), HLA-B gene (9%), EP300 (16%), FBXW7 (15%), NFE2L2 (4%), and ERBB2 (6%) of 79 squamous carcinomas, and ELF3 (13%) and CBFB (8%) mutations in 24 adenocarcinomas." (PMID 26701206, 2016). "Although FBXW7‐deficient keratinocytes proliferate excessively in vitro, loss of FBXW7 does not activate keratinocytes to differentiate into squamous cell carcinoma (SCC) in vivo, triggered by the expression of oncogenic Ras." (PMID 33822486, 2021).
bladder cancer (9 papers, 2012 to 2025). "High FBXW7 levels were linked to longer OS in individuals with bladder cancer." (PMID 39915362, 2025). "The role of FBXW7 in bladder cancer indicated that targeting FBXW7 is a novel approach for bladder cancer therapy." (PMID 37215134, 2023). "Further investigation of FBXW7 in bladder cancer pathogenesis given its reported involvement in this pathway is of interest." (PMID 23593348, 2013). "Similarly, OSU-T315, an inhibitor of integrin-linked kinase, was observed to inhibit Mcl-1 expression levels via targeting the GSK-3β/FBXW7 axis in bladder cancer cells." (PMID 37215134, 2023). "For instance, the similarity observed between CDKN1A and FBXW7 networks underscores the possibility that cell cycle dysregulation in bladder carcinoma can be achieved by directly inactivating a CDK inhibitor or alternatively, by inactivating a regulatory protein." (PMID 31253832, 2019). "Increased FBXW7 activated GSK-3β phosphorylation and inhibited the expression of SREBP1a in bladder cancer cells." (PMID 37215134, 2023). "Stevioside was identified by high-throughput screening as a useful compound to increase cell apoptosis via activation of GSK-3β and induction of FBXW7, contributing to downregulation of MCL-1 in bladder cancer." (PMID 37215134, 2023). "The pathway view of genes frequently altered in bladder carcinoma generated by TCGA1 coheres with this observation, as both CDKN1A and FBXW7 are listed as negative regulators of CCNE1 and cell cycle progression." (PMID 31253832, 2019). "However, we also identified mutations in two other genes not reported in COSMIC for bladder cancer, ATM and FBXW7." (PMID 23593348, 2013).
lung adenocarcinoma (9 papers, 2015 to 2025). A carcinoma that arises from the lung and is characterized by the presence of malignant glandular epithelial cells. "Of note, Liza C. et.al reported a lung adenocarcinoma patient with FBXW7 deficiency both clinically and radiographically benefited from treatment with the mTOR inhibitor." (PMID 25749036, 2015). "It has been reported that m6A modification of FBXW7 mRNA by METTL3 upregulates FBXW7 protein levels in lung adenocarcinoma." (PMID 40169588, 2025). "By analysis of TCGA data, 30.9% of lung adenocarcinoma presents FBXW7 deletion, and 63.5% of lung squamous cell carcinoma exhibited FBXW7 deletion." (PMID 36874015, 2023). "For example, FBXW7 is also up-regulated in 6 other cancers including three types of kidney cancer, lung adenocarcinoma, and thyroid carcinoma." (PMID 31351478, 2019). "Through analysis of The Cancer Genome Atlas data, we show that deletion of FBXW7 occurs in 30.9% of lung adenocarcinomas and 63.5% of lung squamous cell carcinomas, which significantly leads to decrease in FBXW7 mRNA expression." (PMID 29633504, 2018). "However, FBXW7 is also up-regulated in 6 other cancers including three types of kidney cancer, lung adenocarcinoma, and thyroid carcinoma." (PMID 31351478, 2019). "Our primary screen generated a functionally annotated list of 28 genes that led to robust metastatic dissemination and merit further interrogation, including some that have been previously identified to be mutated in lung adenocarcinoma (GNAS, MAPK6, ACVR1B, FBXW7, NTRK3)." (PMID 30013058, 2018). "Gene mutations observed differ between lung adenocarcinoma and lung squamous cell carcinoma, with KRAS, EGFR, LPHN3, KEAP1, and TLR4 being relatively common in lung adenocarcinoma, whereas BAI3, FBXW7, GRM8, ERBB4, MUC16, and RUNX1T1 are common in lung squamous cell carcinoma." (PMID 39594843, 2024).
thymic lymphomas (9 papers, 2010 to 2024). "In mice with Fbxw7 deficiency, microarray dada from radiation-induced thymic lymphomas revealed that 372 lncRNAs are differentially expressed in tumor tissues." (PMID 35928868, 2022). "One study identified that several lncRNAs are correlated with Fbxw7 deficiency in radiation-mediated thymic lymphoma." (PMID 35928868, 2022). "Here we used transcript profiling of radiation induced thymic lymphomas to investigate the molecular signaling pathways that contribute to tumorigenesis in Fbxw7 heterozygous mice and their dependence on mTOR." (PMID 26575021, 2015). "Conditional deletion of Fbxw7 in CD4+ cells, or deletion of Nr4a3 and the closely related Nr4a1, resulted in hyper-proliferation of T cells, thymic lymphoma's and lethal lymphoproliferation, a phenotype similar to Foxp3−/− mice." (PMID 23825948, 2013).
head and neck squamous cell carcinoma (8 papers, 2017 to 2025). A squamous cell carcinoma that arises from any of the following anatomic sites: lip and oral cavity, nasal cavity, paranasal sinuses, pharynx, larynx, and salivary glands. "A phase 1 clinical trial (NCT01115790) of single-agent prexasertib in head and neck squamous cell carcinoma (HNSCC) and squamous cell carcinoma of the anus (SCCA) identified loss-of-function (LOF) mutations in the E3 ubiquitin ligase FBXW7 in patients with clinical benefit." (PMID 32076484, 2020).
lymph node metastasis (8 papers, 2012 to 2025). "A significant reduction in FBXW7 mRNA level was also associated with the presence lymph node metastasis (p = 0.015) and tumor stage III-IV (p = 0.008)." (PMID 24053468, 2013). "Interestingly, in a meta-analysis studying 4199 CRC patients, it was stated that FBXW7 mutations were associated with advanced T stages and lymph node metastases." (PMID 37064111, 2023). "Similarly, in intrahepatic cholangiocarcinoma (IHCC), FBXW7 expression is associated with disease stage, lymph node metastasis, three-year survival rates, and overall and disease-free survival." (PMID 30086763, 2018). "Moreover, deregulated MYC and FBXW7 mRNA expression was associated with the presence of lymph node metastasis and tumor stage III-IV." (PMID 24053468, 2013). "In addition, FBXW7 mRNA expression deregulation was associated with the presence of lymph node metastasis and GC stage III-IV, as was also observed with MYC mRNA." (PMID 24053468, 2013). "Altered FBXW7 status was associated with advanced T stage and lymph node metastasis in CRC, and low FBXW7 mRNA/protein level indicates poor OS in CRC." (PMID 34217244, 2021). "In the univariate analysis, other significant prognostic factors for cancer-specific survival included lymph node metastasis (P=0.008), lymphatic invasion (P=0.002), and FBXW7 expression (P=0.023)." (PMID 22108521, 2012).
T-cell lymphoma (8 papers, 2008 to 2025). "FBXW7 is a haplo-insufficient tumor suppressor gene recently shown to be frequently inactivated in T cell lymphomas by mutation or deletion." (PMID 18394558, 2008). "FBXW7 has been identified as a tumor suppressor gene and is correlated with a worse prognosis in T-cell lymphomas." (PMID 39943162, 2025). "In support of a role in oncogenesis, FBXW7 is somatically altered in >30% of human T-cell lymphomas, while T-cell-specific Fbxw7 knockout mice develop ALL." (PMID 35345853, 2022). "Finally, in T-cell lymphomas, considered to be those with the most aggressive behavior, the SATB1 and FBXW7 genes were frequently mutated." (PMID 39943162, 2025). "Notably, FBXW7 is much more recurrently mutated in Gr B-cell than Cs B-cell lymphomas, and it is also mutated in a few Gr T-cell lymphomas but none of the studied Bx T-cell lymphomas." (PMID 26377837, 2015).
triple-negative breast carcinoma (8 papers, 2015 to 2024). An invasive breast carcinoma which is negative for expression of estrogen receptor (ER), progesterone receptor (PR), and human epidermal growth factor receptor 2 (HER2). "CircFBXW7, which acts as a sponge for miR-197-3p, encodes the FBXW7-185aa protein, which suppresses triple-negative breast cancer (TNBC) progression by upregulating FBXW7 expression." (PMID 34110722, 2021). "A small number of previous studies indirectly mentioned the role of F-box and WD repeat domain-containing 7 (FBXW7) as a tumor suppressor in Triple-negative breast cancer (TNBC)." (PMID 38268032, 2024). "The circFBXW7 encodes FBXW7–185AA, which under the mediation role of IRES, regulates the expression of FBXW7 and exerts a tumor suppressor effect in triple-negative breast cancer (TNBC)." (PMID 37124497, 2023). "Another study discovered two pathways in triple-negative breast cancer to control the expression of FBXW7: One displayed that circ-FBXW7 sponges miR-197-3p to promote the expression of FBXW7." (PMID 35814468, 2022). "A recent study has noted that miR-197-3p forms a ceRNA network by connecting circular F-box and WD repeat domain containing 7 (FBXW7) and FBXW7-185aa protein to mediate triple-negative breast cancer progression, corroborating that miR-197-3p is a capable factor in ceRNA mechanism." (PMID 34793477, 2021).
Wilms tumor (8 papers, 2014 to 2024). An embryonal neoplasm characterized by the presence of epithelial, mesenchymal, and blastema components. "We provided evidence that constitutional FBXW7 mutations predisposed to Wilms tumour and to other malignancies." (PMID 30885698, 2019). "FBXW7 is highly intolerant to protein-truncating variants (pLI=1·00) and these data suggest that FBXW7 is a Wilms tumour predisposition gene." (PMID 30885698, 2019). "Similarly, in humans, germline variants in FBXW7 are strongly associated with predisposition to early onset cancers, such as Wilms tumors and Hodgkin’s lymphoma." (PMID 33090996, 2020). "Analyzing exome sequencing of lymphocyte DNA from Wilms tumor involving 890 individuals has shown that TRIM28, FBXW7, KDM3B, and NYNRIN are new predisposition genes of Wilms tumor." (PMID 38926399, 2024). "The four new Wilms tumour predisposition genes identified—TRIM28, FBXW7, NYNRIN, and KDM3B—are involved in diverse biological processes and, together with the other 17 known Wilms tumour predisposition genes, account for about 10% of Wilms tumour cases." (PMID 30885698, 2019). "A further five constitutionally mutated genes—PIK3CA, FBXW7, ASXL1, BRCA2, and CDC73—were somatically mutated in other cancer types but have not been proven to be somatic drivers in Wilms tumour." (PMID 30885698, 2019).